PON1 (paraoxonase 1)
Diseases named in the same sentence as PON1 in open-access papers (continued):
Sharing a sentence is not in itself a finding about the gene and the disease.
fetal growth restriction (2 papers, 2011 to 2013). A fetus that does not grow beyond the 10th percentile of conventionally accepted weight for gestational age. "Serum PON1 activity was higher in preeclamptic group (P = 0.040) and preeclamptic group without intrauterine growth restriction (P = 0.008) compared to normal pregnant women." (PMID 23606795, 2013).
glaucoma (2 papers, 2020 to 2025). Increased pressure in the eyeball due to obstruction of the outflow of aqueous humor. "Current literature has stated that although more research is needed to elucidate the role of PON1 function regarding glaucoma, it is reasonable to suppose that PON1 function is clinically important, despite being difficult to prove statistically." (PMID 32331355, 2020). "Comparative studies demonstrate elevated oxidative status, stress indices, and TC in normal-tension and pseudoexfoliation glaucoma patients versus controls, with altered PON1 enzyme activity 111, suggesting oxidative stress and dyslipidemia contribute across glaucoma subtypes." (PMID 41049435, 2025). "Studies have been exploring the role of human serum paraoxonase 1 (PON1) in glaucoma." (PMID 32331355, 2020).
glioblastoma (2 papers, 2021 to 2024). The most malignant astrocytic tumor (WHO grade IV). "In our study, we determined the effects of PON1 enzyme activity on the proliferation and aggressiveness of glioblastoma cancer treated with TQ and EF-24 from lysates of the glioblastoma cell line U87MG." (PMID 38864175, 2024).
hyperthyroidism (2 papers, 2020). Overactivity of the thyroid gland resulting in overproduction of thyroid hormone and increased metabolic rate. "The increase in Lp(a) and the decrease in PON-1 activity that are important risk factors were documented here in subclinical hyperthyroidism and these results should be confirmed in larger studies due to great data variation but should not be neglected in the follow-up of those patients." (PMID 32300332, 2020). "PON1 activity (decreased 75%, p = 0.0006) was lower in subclinical hyperthyroidism." (PMID 32300332, 2020).
Hypoalbuminemia (2 papers, 2024). The concentration of albumin in the blood circulation is below the lower limit of normal. "Significant differences among groups between PON-1 concentration and hypoalbuminemia groups were found (p = 0.0018)." (PMID 39518842, 2024). "Similarly, hypoalbuminemia and a decrease in other negative APPs such as transferrin (or total iron-binding capacity: TIBC) and paraoxonase 1 (PON-1) were reported." (PMID 39444011, 2024).
iron deficiency (2 papers, 2019 to 2024). "PON1 activity is lower in patients with iron deficiency and increases after iron treatment." (PMID 39684839, 2024).
ischemia (2 papers, 2017 to 2020). A hypoperfusion of the BLOOD through an organ or tissue caused by a PATHOLOGIC CONSTRICTION or obstruction of its BLOOD VESSELS, or an absence of BLOOD CIRCULATION. "In patients undergoing coronary intervention with no-reflow, an I/R event, blood PON1 activity was lower after ischemia than that in patients with normal flow." (PMID 28553435, 2017).
kidney cancer (2 papers, 2019 to 2024). Primary or metastatic malignant neoplasm involving the kidney. "PON1 enzyme is involved in antitumor response; it inhibits migration, invasion and proliferation of kidney cancer cells and suppresses tumor growth." (PMID 39896931, 2024). "The results indicated that the mRNA levels in the three kidney cancer cell lines (786‐O cells, Caki‐2 cells and SKRC39) were down‐regulated in comparison with HK‐2 cells and the protein level of PON1 displayed the same trend." (PMID 31400051, 2019).
leukaemia (2 papers, 2017 to 2020). "We have found that NQO1 C609T modified risk in pediatrics leukaemia depending on age range and the variant genotype in combinations with other gene polymorphisms, such as Paraoxonase 1 (PON1) gene variant." (PMID 29225689, 2017). "We have investigated NQO1 and PON1 polymorphisms associated with early-age leukaemia considering acquiring genomic aberrations and age at the onset of the disease." (PMID 29225689, 2017).
lung adenocarcinoma (2 papers, 2017 to 2025). A carcinoma that arises from the lung and is characterized by the presence of malignant glandular epithelial cells. "Mining several meta-analyses of oncogenomic/transcriptomic datasets derived from the TCGA databases, we found a higher frequency of differential gene expression (copy numbers) of PON1 between SCC and lung adenocarcinoma cohorts across all variants per subtype." (PMID 28467805, 2017). "Although minimal in protein overexpression, PON1 is expressed in SCC while infrequently deleted in lung adenocarcinoma." (PMID 28467805, 2017). "In a broad context, higher amplified copy numbers of PON1 were detected in SCC than lung adenocarcinoma cohorts while infrequent, higher deletion frequency in lung adenocarcinoma than SCC cohorts." (PMID 28467805, 2017). "Similarly, a meta-analysis of lung adenocarcinoma patients showed that low PON1 expression correlated with lower overall survival but better progression-free survival, underscoring its complex prognostic role." (PMID 40469570, 2025). "In the adenocarcinoma cohort, PON1 is slightly amplified in general lung adenocarcinoma samples (261 samples) and mixed subtype lung adenocarcinoma (67 samples) but deleted in lung clear cell adenocarcinoma (2 samples) and lung mucinous adenocarcinoma (6 samples)." (PMID 28467805, 2017). "Tissue-based protein expression analysis revealed that PON1 has a varied expression pattern between squamous cell carcinoma (SCC) and lung adenocarcinoma tissues." (PMID 28467805, 2017). "Interestingly, we identified in this study that there is a varied PON1 protein expression pattern between our cohorts of SCC and lung adenocarcinoma patient tissue samples matched with adjacent normal tissues." (PMID 28467805, 2017).
lung disease (2 papers, 2017 to 2023). "In our previous efforts in studying the implication of PON1 in LC, we recently discovered that serum PON1 is a highly significant meta-marker, along with SERPINA4, for the differential diagnosis of LC and lung disease." (PMID 28467805, 2017). "Importantly, the assessment of PON1 activity and bioactive lipid mediators was done approximately 5 years prior to the CT scan and therefore does not reflect the patient’s PON1 activity and levels of oxidative stress at the time the pulmonary disease was identified." (PMID 36138190, 2023).
male idiopathic infertility (2 papers, 2019 to 2021). "They showed that Q192R polymorphisms of PON1 gene are associated with a reduction in the risk of male idiopathic infertility, which are not consistent with our results on the RPL in women." (PMID 34401650, 2021).
mastitis (2 papers, 2021 to 2026). Inflammation of breast tissue during lactation or postpartum due to an obstructed duct or infection. "Biomarkers such as lactoferrin (LTF), β-defensin 4 (DEFB4), vitronectin, paraoxonase 1 (PON1), and N-acetyl-β-D-glucosaminidase (NAGase) show promise in distinguishing between cows not susceptible and cows susceptible to mastitis." (PMID 41594349, 2026). "Therefore, paraoxonase-1 activity could be considered as a potential biomarker for diagnosing subclinical mastitis." (PMID 33509059, 2021).
mixed connective tissue disease (2 papers, 2018 to 2022). Mixed connective tissue disease (MCTD) is a rare autoimmune disorder that is characterized by features commonly seen in three different connective tissue disorders: systemic lupus erythematosus, scleroderma, and polymyositis. "Mixed connective tissue disease (MCTD) seems to exhibit an exceptionally high prevalence of anti-HDL positivity, and an association between anti-HDL antibodies and impaired PON1 activity in MCTD has been postulated." (PMID 35847825, 2022).
nephrotic syndrome (2 papers, 2013 to 2023). A collection of symptoms that include severe edema, proteinuria, and hypoalbuminemia; it is indicative of renal dysfunction. "The positive association between albumin and PON-1 has been described in dogs and humans in various diseases such as parvovirus enteritis and nephrotic syndrome." (PMID 36669034, 2023). "The aim of the present study was to investigate the serum activities of paraoxonase-1 (PON-1), and aryleterase (ARE) as well as total antioxidant capacity (TAC) in children with nephrotic syndrome in acute and remission phase." (PMID 24693505, 2013).
Pca (2 papers, 2013 to 2020). "In the present study, serum PON1 levels in patients with PCa were significantly lower compared to healthy individuals and patients with BPH." (PMID 32549522, 2020). "In a case/control study whose cohorts has now been included in the present enlarged populations, we previously found that polymorphisms in oxidative-stress control-related GSTP1, PON1-192, PON-1 55 and CYP17 genes were associated with the risk of PCa." (PMID 24040147, 2013). "The present study investigated differences in PON1 and PON3 activities and serum MDA levels and lipid profile levels between patients with Pca, patients with benign prostatic hyperplasia (BPH) having previously undergone RALRP, and a control group." (PMID 32549522, 2020). "In contrast, ARE activity remained normal in patients with PCa, while PON1 activity increased." (PMID 32549522, 2020). "Low PON1 activity in PCa patients may be a result of high ROS activity in PCa." (PMID 32549522, 2020). "The mechanism involved in the decrease in PON1 and ARE activities in PCa patients is still unclear." (PMID 32549522, 2020). "PON1 and PON3 increased postoperatively in the PCa group, while MDA decreased." (PMID 32549522, 2020). "PON1 and PON3 levels decreased significantly in patients with PCa, while MDA levels increased." (PMID 32549522, 2020). "The present study compared paraoxonase (PON1, PON3), PON1/HDL, triglyceride, HDL, LDL, and MDA levels in patients with PCa among individuals with BPH, undergoing RARLP, with no biochemical recurrence and a control group." (PMID 32549522, 2020).
peritonitis (2 papers, 2016 to 2021). Inflammation of the peritoneum (tissue that lines the abdominal wall and covers most of the organs in the abdomen). "That MPO impacts PON1 activity in vivo was previously demonstrated using i.p. injection of zymosan to induce peritonitis." (PMID 34331945, 2021).
psychosis (2 papers, 2023 to 2025). "Subsequently, a study in 2022 found that the decrease in PON1 activity would participate in the occurrence of psychotic disorders (including psychosis, anxiety, depression, etc.)by increasing oxidative stress in patients with TLE and MTS comorbid with mental disorders." (PMID 39858450, 2025).
pulmonary hypertension (2 papers, 2017 to 2018). Increased pressure within the pulmonary circulation due to lung or heart disorder. "This relationship between CRP and pulmonary hypertension was supported by the results of another study, which also evaluated haptoglobin, albumin and PON-1, and confirmed the relationship between pulmonary hypertension and acute phase response, especially in the positive APP CRP and haptoglobin." (PMID 29143665, 2017).
renal dysfunction (2 papers, 2019 to 2024). "PON1 activity is negatively affected by oxidative stress, and it is possible that higher uric acid concentrations observed in patients with renal dysfunction may protect, to some extent, PON1 from oxidative stress." (PMID 30886652, 2019).
retinal vein occlusion (2 papers, 2013 to 2024). An occlusion of the retinal vein. "Genotypic and allelic distribution of PON1 55L/M and PON1 192Q/R polymorphisms among patients with retinal vein occlusion and control subjects." (PMID 23441121, 2013).
rosacea (2 papers, 2020 to 2023). A chronic erythematous skin disorder that affects the face. "Low serum activity of paraoxonase-1 (PON-1), an antioxidant enzyme that prevents oxidation of serum lipoprotein, is a shared feature between rosacea and metabolic disease and suggests that oxidative stress contributes to their co-occurrence." (PMID 33080929, 2020).
sickle cell disease (2 papers, 2019 to 2023). Sickle cell anemias are chronic hemolytic diseases that may induce three types of acute accidents: severe anemia, severe bacterial infections, and ischemic vasoocclusive accidents (VOA) caused by sickle-shaped red blood cells obstructing small blood vessels and capillaries. "The PON-1 Q192R and R192R polymorphism frequencies were higher in the sickle cell disease group, whereas Q192Q genotype frequency was higher in the healthy control group." (PMID 31366068, 2019). "The higher frequency of the RR homozygotes of the PON-1 Q192R polymorphism and the low frequency of the QQ and QR genotypes in patients with sickle cell disease, compared with healthy controls, were unexpected." (PMID 31366068, 2019). "Examining the PON-1 Q192R polymorphism, however, the arylesterase activity was lower only in QR sickle cell disease patients, compared with healthy subjects." (PMID 31366068, 2019). "Paraoxonases 1, 2, and 3 polymorphisms, and PON-1 activities were evaluated in patients with sickle cell disease." (PMID 31366068, 2019). "The biochemical and hematological parameters were also evaluated in relation to the PON-1 Q192R polymorphism in sickle cell disease patients (QQ, QR, and RR phenotypes)." (PMID 31366068, 2019). "It is tempting to postulate that both transferrin and ferritin could be a link between the inflammatory process underlying sickle cell disease and serum PON-1 activities." (PMID 31366068, 2019). "Moreover, in this study, sickle cell disease patients with PON-1 RR polymorphism had a lower serum ferritin and iron concentration and transferrin saturation when compared with those with QQ or QR polymorphisms." (PMID 31366068, 2019). "The allele distribution of the PON-1, PON-2, and PON-3 polymorphisms followed the Hardy–Weinberg equilibrium in the sickle cell disease group as well as in the healthy control group." (PMID 31366068, 2019). "Here, for the first time, the arylesterase and paraoxonase activities of PON-1 were evaluated, as well as the frequency of the polymorphism in PON-1, PON-2, and PON-3 genes, in patients with sickle cell disease." (PMID 31366068, 2019). "Although both arylesterase and paraoxonase PON-1 activities were reduced in patients with sickle cell disease compared with healthy controls, only arylesterase activity reached the significance level." (PMID 31366068, 2019). "Nevertheless, further research is needed to better understand the relationship between cholesterol metabolism, iron metabolism, and PON-1 in sickle cell disease." (PMID 31366068, 2019). "In this study, total cholesterol, HDL-C, LDL-C, Apo-A1, and Apo-B, as well arylesterase PON-1 activity were decreased in sickle cell disease patients." (PMID 31366068, 2019). "Here, for the first time, we described PON-1 activities and PON-1, PON-2, PON-3 polymorphisms in patients with sickle cell disease, homozygous for HbSS, compared with healthy controls." (PMID 31366068, 2019). "Although these data might indicate that the PON-1 QQ phenotype could be related to a more severe form of sickle cell anemia, more studies should be performed." (PMID 31366068, 2019). "Regarding the PON-1 L55M polymorphism, the arylesterase activity was lower in LL and LM patients with sickle cell disease compared with healthy individuals, while it was not changed in MM patients." (PMID 31366068, 2019). "Therefore, the decreased PON-1 activities in patients with sickle cell disease observed in this study may be due, at least in part, to alterations in HDL and apo-A1 structures." (PMID 31366068, 2019).
systemic inflammatory response syndrome (2 papers, 2020). SIRS is a serious condition related to systemic inflammation, organ dysfunction, and organ failure. "Interestingly, in a further study, low PON-1 activity was reported only in some of the horses with systemic inflammatory response syndrome (SIRS)." (PMID 33148245, 2020).
ulcerative colitis (2 papers, 2007 to 2018). An inflammatory bowel disease involving the mucosal surface of the large intestine and rectum. "A study indicates that the mechanism of the observed decrease in the activity of PON-1 in the serum of patients with ulcerative colitis is due to the natural capacity of the organism to protect against LDL oxidation, which is accompanied by the deactivation of the enzyme." (PMID 30314292, 2018).
viral hepatitis (2 papers, 2010 to 2022). An acute or chronic inflammation of the liver parenchyma caused by viruses. "In line with the previous authors, there was decrease in PON1 activity in acute viral hepatitis patients." (PMID 20339175, 2010).
acute monocytic leukemia (1 paper, 2026). Acute monoblastic leukemia (AML-M5), is one of the most common subtypes of acute myeloid leukemia (AML) that is either comprised of more than 80% of monoblasts (AML-M5a) or 30-80% monoblasts with (pro)monocytic differentiation (AML-M5b). "The effect of MPO, PON1, and serums from the individuals with ASCVD and healthy individuals on cholesterol efflux of human acute monocytic leukemia cell line (THP-1 cells) was compared." (PMID 41704870, 2026).
alcohol addiction (1 paper, 2023). "Our study is the first to have investigated and revealed an association between PON1 rs705381 and social phobia in patients with alcohol addiction and compulsion in healthy individuals." (PMID 38275640, 2023). "However, to our knowledge, there are no studies that focus on the genetic variability of PON1, SOD2, GPX1, IL1B, IL6, interleukin 6 receptor (IL6R), and miR146a related to the risk of alcohol addiction, and patients’ comorbid psychosymptomatology." (PMID 38275640, 2023). "Thus, we focused on the role of PON1 rs705379, rs705381, rs854560, and rs662, SOD2 rs4880, GPX1 rs1050450, IL1B rs1143623, rs16944, and rs1071676, IL6 rs1800795, IL6R rs2228145, and miR146a rs2910164 in alcohol addiction, and patients’ comorbid psychosymptomatology." (PMID 38275640, 2023).
alcoholic liver cirrhosis (1 paper, 2023). A disorder of the liver characterized by the presence of fibrotic scar tissue instead of healthy liver tissue. "Decreased PON1 enzyme activity was observed in alcoholic liver cirrhosis, chronic hepatitis, and NASH." (PMID 37908943, 2023).
aneurysm (1 paper, 2023). Bulging or ballooning in an area of an artery secondary to arterial wall weakening. "The vector of the analyzed interaction reveals the role of NRF2 as a transmitter of information between HO-1, bilirubin, and PON1, i.e., the parameters whose participation in the development of an aneurysm has been described as potentially significant." (PMID 37627563, 2023). "The analysis of individual study groups, which we propose, considering the aneurysm size, allows us to observe the significance of PON1 concentration." (PMID 37627563, 2023). "The continuing trend of increasing PON1 concentration with increasing aneurysm size may also refer to its role as an acute phase protein, which has already been described in our previous work." (PMID 37627563, 2023). "A trend towards a significant positive correlation between PON1 and aneurysm diameter was observed." (PMID 37627563, 2023). "The correlation matrix analysis of parameters in the study group, without categorization into the stage of aneurysm, shows a number of correlations in which the PON1 concentration plays a key role." (PMID 37627563, 2023).
aortic atherosclerosis (1 paper, 2021). A atherosclerosis that involves the aorta. "Recently, among the Han population in China, researchers found that PON1 rs662 was a potential AIS risk, especially in males with aortic atherosclerosis." (PMID 33628379, 2021).